ZNF185 (zinc finger protein 185 with LIM domain)
Description:
May be involved in the regulation of cellular proliferation and/or differentiation.
Synonyms: SCELL
Tractability: Antibody: the Human Protein Atlas places it where antibodies can reach. PROTAC: ubiquitination databases record sites on it; its protein half-life has been measured.
Gene: Protein-coding gene on chromosome X (152,896,695 to 152,973,511, forward strand). Ensembl gene ENSG00000147394.
Subcellular location: Cytoplasm, cytoskeleton; Cell junction, focal adhesion
Subcellular location (Human Protein Atlas): Cytosol; Plasma membrane; Actin filaments; Focal adhesion sites
Gene Ontology:
Molecular function: protein binding; zinc ion binding
Cellular component: actin cytoskeleton; cytosol; focal adhesion; plasma membrane; cytoskeleton
Homologues: Orthologues: chimpanzee ZNF185 (98% identical), macaque ZNF185 (89% identical), pig ZNF185 (71% identical), dog ZNF185 (69% identical), guinea pig ZNF185 (59% identical), rat Zfp185 (50% identical), mouse Zfp185 (44% identical), zebrafish znf185 (22% identical), tropical clawed frog slain2l (16% identical). Paralogues in human: SCEL (15% identical).
Diseases named in the same sentence as ZNF185 in open-access papers:
ZNF185 is named in the same sentence as 27 diseases in open-access papers, as found by Europe PMC text mining. Sharing a sentence is not in itself a finding about the gene and the disease. The quoted sentences say what the papers report.
prostate carcinoma (11 papers, 2007 to 2025). A carcinoma that arises from epithelial cells of the prostate gland. "Similarly, the reduced expression of FCMD, which was reported to be involved in brain development, and ZNF185, a tumor-suppressor protein associated with actin-cytoskeleton and reported in prostate cancer, was observed in our studies." (PMID 23056957, 2012). "For instance, some studies have suggested that ZNF185 acts as a tumor suppressor in prostate cancer, while others have proposed that the low expression of ZNF185 serves as a negative prognostic marker for colorectal cancer." (PMID 40136427, 2025). "By using a cell growth and soft agar colony formation assay, San and coauthors investigated the role of ZNF185 in the initiation and growth of prostate cancer." (PMID 38827026, 2024). "They found that, when the ZNF185 gene was overexpressed through a transfection experiment, the gene had a major antitumor effect on the progression of prostate cancer cells and colony formation in soft agar." (PMID 38827026, 2024). "Zn finger protein ZNF185 is a LIM domain gene the expression of which is downregulated in several epithelial cancers including prostate cancer." (PMID 36551962, 2022). "The expression level of ZNF15 has a negative correlation with prostate cancer progression, and the methylation of the 5′CpG islands of the ZNF185 gene has a close relationship with metastasis of prostate cancer." (PMID 35813821, 2022). "It was previously reported that ZNF185 regulates proliferation of prostate cancer cells, to further investigate this point we generated Ker-CT cell line, stably expressing shRNA against ZNF185 (shZNF185)." (PMID 30446632, 2018). "Additionally, in cases of prostate cancer, cranio-cervical squamous cell carcinoma, and non-small-cell lung cancer, ZNF185 expression has been shown to be significantly lower (downregulated) in healthy (non-cancerous) tissues." (PMID 40136427, 2025). "The ZNF185 gene, affected by a splicing mutation specifically in both metastases of PTID 4, is suggested to function as a tumor suppressor by associating with the actin-cytoskeleton and is reported to be associated with metastatic progression in colon and prostate cancer." (PMID 29293529, 2018). "Interestingly, ZNF185 expression is reduced in prostate cancer owing to DNA methylation." (PMID 29152378, 2017). "For example, patients with high expression of ZNF185 have better DFI (Disease Free Interval) and PFS (Progression Free Survival) in prostate cancer." (PMID 41081583, 2025).
squamous cell carcinoma (5 papers, 2018 to 2024). A carcinoma arising from squamous epithelial cells. "Interestingly, poorly differentiated, including head and neck, cervical and oesophageal, squamous cell carcinomas display loss of ZNF185 expression." (PMID 30337687, 2019). "In mice, ZNF185 can act as a target gene of p63 to regulate the dynamic balance of epidermal differentiation and the occurrence of squamous carcinoma." (PMID 38584846, 2024). "A previous study showed that ZNF185 silencing strongly impaired keratinocyte differentiation in the head and neck, and in cervical and squamous cell carcinomas, however, functions for ZNF146 have remained unclear to date." (PMID 32849815, 2020). "Since ZNF185 physically interacts with E-cadherin, we asked whether ZNF185 could also be modulated in squamous cell carcinomas." (PMID 30337687, 2019). "Interestingly, E-cadherin and ZNF185 expression levels are strongly downregulated in poorly differentiated, including head and neck, cervical and oesophageal, squamous cell carcinomas." (PMID 30337687, 2019). "Furthermore, ZNF185 was found only in well-differentiated subpopulations of squamous cell carcinoma (“WD” of cSCC) in contrast to poorly-differentiated basal-like subpopulations (“PD” of cSCC)." (PMID 30446632, 2018). "Moreover, we found ZNF185 positive signal only in well-differentiated subpopulations of squamous cell carcinoma in contrast to poorly-differentiated basal-like aggressive subpopulations, suggesting a tumour-suppressor role of ZNF185." (PMID 30446632, 2018).
pancreatic cancer (4 papers, 2020 to 2025). "In the prognostic risk model of this study, ZMAT1 is a low-risk gene for pancreatic cancer, while PRKCI and ZNF185 are high-risk genes for pancreatic cancer." (PMID 37396042, 2023). "Pancreatic cancer HEAT repeat-containing protein 1 (HEATR1) deficiency can affect pancreatic cancer chemotherapy sensitization via the upregulation of ZNF185." (PMID 37396042, 2023). "Expression of ZNF185 at the plasma membrane is associated with an unfavorable prognosis in patients with pancreatic cancer." (PMID 34421347, 2021). "From the multivariate survival analysis, we observed that high TNM staging, poorer differentiation, higher staining of HEATR1, or lower staining of ZNF185 in pancreatic cancer were the independent prognostic factors of pancreatic cancer patients." (PMID 32565799, 2020). "Our observation is the first to identify a relationship between ZNF185 regulation and gemcitabine chemosensitivity of pancreatic cancer." (PMID 32565799, 2020). "By high-content screening (HCS), we confirmed that knocking down ZNF185 in the pancreatic cancer cells could promote the chemosensitivity of gemcitabine." (PMID 32565799, 2020). "Moreover, we also preliminarily discovered that knocking down ZNF185 served as increasing the chemosensitivity via SMAD4 in pancreatic cancer which was confirmed by in vitro and in vivo analysis." (PMID 32565799, 2020). "Moreover, we found that after knocking down ZNF185, the pancreatic cancer cells in the S phase and the G2/M phase increased, while the cells in the G1 phase decreased, both of which indicated that the cellular proliferation was inhibited in the S phase." (PMID 32565799, 2020). "Here, we found that knocking down ZNF185 could synergistically promote the chemosensitivity of gemcitabine in pancreatic cancer cells." (PMID 32565799, 2020). "Importantly, the role of ZNF185 in pancreatic cancer is dependent on its subcellular localization." (PMID 34421347, 2021). "Besides, the relevance of our study was confirmed in the samples of pancreatic cancer patients, and we demonstrated that HEATR1, ZNF185, and SMAD4 expression are significantly associated with the prognosis with pancreatic cancer in the patients treated with gemcitabine chemotherapy." (PMID 32565799, 2020). "Taken together, it is the first time to reveal that HEATR1, ZNF185, and SMAD4 are correlated in the chemosensitivity of gemcitabine in pancreatic cancer." (PMID 32565799, 2020). "We confirmed the chemosensitive function of ZNF185 by observing the elevation of apoptotic percentage and proliferative inhibition of pancreatic cancer cells after knocking down both HEATR1 and ZNF185 and treated with gemcitabine." (PMID 32565799, 2020). "Moreover, ZNF185 contributes to chemotherapy resistance, in combination with elevated SMAD4 expression, in pancreatic cancer." (PMID 34421347, 2021). "HEATR1, ZNF185, and SMAD4 could affect the chemosensitivity of gemcitabine and may be the indicators of gemcitabine selection in the chemotherapy of pancreatic cancer." (PMID 32565799, 2020).
head and neck squamous cell carcinoma (3 papers, 2018 to 2020). A squamous cell carcinoma that arises from any of the following anatomic sites: lip and oral cavity, nasal cavity, paranasal sinuses, pharynx, larynx, and salivary glands. "Epigenetic silencing of ZNF185 has been associated with high-grade and metastatic prostate tumours, lung tumours, and head and neck squamous cell carcinomas." (PMID 30337687, 2019). "On the other hand, other studies described epigenetic silencing of ZNF185 associated with high grade and metastatic prostate tumours, lung tumours and head and neck squamous cell carcinomas." (PMID 30446632, 2018). "At mRNA and protein level, ZNF185 is strongly reduced in different types of epithelial tumours, including skin and head and neck squamous cell carcinomas, suggesting that depletion of ZNF185 in cancer cells facilitate cancer cell migration and spreading." (PMID 30446632, 2018). "The knowledge about the function of ZNF185 is still lacking, while some previous studies have shown its role in cell proliferation, cell differentiation, and cell apoptosis in the prostate, lung, and head and neck squamous cell carcinoma." (PMID 32565799, 2020).
lung adenocarcinoma (3 papers, 2018 to 2021). A carcinoma that arises from the lung and is characterized by the presence of malignant glandular epithelial cells. "Recently, it was reported that ZNF185 expression is negatively correlated with lymph node metastasis of lung adenocarcinoma and its overexpression leads to down-regulation of p-AKT, p-GSK3β, VEGF and MMP-9 expression." (PMID 30446632, 2018).
cervical squamous cell carcinoma (2 papers, 2019 to 2025). A squamous cell carcinoma arising from the cervical epithelium. "Analysis of oesophageal and cervical squamous cell carcinoma confirmed ZNF185 downregulation at protein level." (PMID 30337687, 2019).
colon cancer (2 papers, 2017 to 2021). "ZNF185 expression is reportedly an independent predictor of both prognosis and liver metastasis in patients with colon cancer." (PMID 34421347, 2021).
esophageal cancer (2 papers, 2021 to 2023). A primary or metastatic malignant neoplasm involving the esophagus. "Therefore, we concluded that UBE3A interacted with ZNF185 and was negatively associated with the protein level of ZNF185 in esophageal cancer." (PMID 34421347, 2021). "In this study, we explored the mechanism underlying post-transcriptional regulation of ZNF185; we found that ZNF185 underwent ubiquitin-dependent proteasome degradation in the presence of UBE3A in esophageal cancer cells." (PMID 34421347, 2021). "Taken together, our data suggested that UBE3A activates the NOTCH pathway via ZNF185 in esophageal cancer cells." (PMID 34421347, 2021). "Together, these results suggested that ZNF185 is a degradation target of UBE3A in esophageal cancer cells." (PMID 34421347, 2021). "MTS and colony formation assays showed that ZNF185 knockdown significantly enhanced the proliferation of esophageal cancer cells." (PMID 34421347, 2021). "Co-immunoprecipitation analyses demonstrated that UBE3A bound to ZNF185 in a reciprocal manner in both Eca-109 and TE-1 esophageal cancer cells." (PMID 34421347, 2021). "The role of UBE3A and ZNF185 in esophageal cancer growth was assessed by MTS assays, colony formation assays, and experiments in mouse xenograft models." (PMID 34421347, 2021). "Here, our results suggested that ZNF185 knockdown led to enhanced cell proliferation among esophageal cancer cells by activation of the NOTCH pathway." (PMID 34421347, 2021). "Taken together, our data indicate that the UBE3A/ZNF185/NOTCH axis is important in the progression of esophageal cancer." (PMID 34421347, 2021). "We further showed that UBE3A degraded ZNF185 to modulate the growth of esophageal cancer cells and activate the NOTCH signaling pathway." (PMID 34421347, 2021). "Furthermore, we found that UBE3A promotes ZNF185 degradation to activate the NOTCH signaling pathway in esophageal cancer cells." (PMID 34421347, 2021). "Finally, we investigated the mechanism by which ZNF185 contributes to the suppression of esophageal cancer, using a transcriptome sequencing approach in a ZNF185 knockdown line of Eca-109 cells." (PMID 34421347, 2021). "Because UBE3A possesses an E3 ligase function, and the protein level of ZNF185 was negatively associated with UBE3A, we hypothesized that UBE3A might be involved in promoting the degradation of ZNF185 in esophageal cancer." (PMID 34421347, 2021). "Additionally, ZNF185 suppressed the progression of esophageal cancer by inactivating the NOTCH pathway." (PMID 34421347, 2021). "Because UBE3A promoted the progression of esophageal cancer cells, we investigated whether ZNF185 influenced the UBE3A-induced tumor growth in esophageal cancer cells." (PMID 34421347, 2021). "Moreover, we found that UBE3A degraded ZNF185 in esophageal cancer." (PMID 34421347, 2021). "Additionally, ZNF185 knockdown greatly enhanced the invasiveness of esophageal cancer cells." (PMID 34421347, 2021). "In contrast, UBE3A overexpression led to reduced protein expression of ZNF185, but did not impact is mRNA expression, in all three esophageal cancer cell lines." (PMID 34421347, 2021). "In consistent, ZNF185 mRNA levels were higher in esophageal cancer tissues than in non-normal tissues from resected esophageal cancer specimens in our hospital through RT-qPCR analysis." (PMID 34421347, 2021). "UBE3A knockdown led to enhanced protein expression of ZNF185, but did not impact its mRNA expression, in all three esophageal cancer cell lines." (PMID 34421347, 2021). "Notably, analysis with the Gene Expression Profiling Interactive Analysis (GEPIA) web tool 20 indicated that ZNF185 was downregulated in esophageal cancer tissues, compared with non-tumor esophageal tissues." (PMID 34421347, 2021).
malignant melanoma (1 paper, 2018). "Analysis of skin cancer samples revealed that ZNF185 expression is dramatically down-regulated in the cutaneous squamous and basal cell carcinoma (“cSCC” and “cBCC”) and malignant melanoma (“cMM”) samples." (PMID 30446632, 2018).
ovarian disorder (1 paper, 2025). A disease involving the ovary. "Notably, ZNF185 mRNA levels were significantly elevated in follicular fluid from endometrioma-affected ovaries compared to contralateral unaffected ovaries, corroborating our in vitro findings and suggesting pathological relevance in human ovarian disorders." (PMID 40877235, 2025).
skin carcinoma (1 paper, 2018).
tumor (22 papers, 2012 to 2025). "We showed that the inhibition of tumor growth caused by UBE3A knockdown could be attenuated by concurrent knockdown of ZNF185, both in vitro and in vivo." (PMID 34421347, 2021). "ZNF185 may function as a tumor-suppressor protein by associating with the actin-cytoskeleton." (PMID 27768594, 2016). "This activation suppresses tumor progression via cytoskeletal remodeling, implicating ZNF185 as a tumor suppressor." (PMID 40877235, 2025). "EPZ004777 downregulated tumor-associated genes such as TPBG, ZNF185, and SNX19, suggesting its ability to inhibit tumor progression." (PMID 40136427, 2025). "Upregulation of ZNF185 has been reported to suppress cell proliferation and given its epigenetic silencing in different tumor cells, this protein has been proposed as a tumor suppressor." (PMID 39119040, 2024). "We confirmed decreased membrane staining of ZNF185 (p-value: 2 × 10−3 and 5 × 10−4) in poorly differentiated tumour cells compared to well-differentiated tumour cells and normal cells of the squamous epithelium." (PMID 30337687, 2019). "Downregulation of ZNF185 expression seems to be a frequent event in several tumour types, suggesting that ZNF185 acts as a tumour-suppressor gene." (PMID 30337687, 2019). "Unexpectedly, we observed that the transcription of ZNF185 is strongly reduced in HNSCC tumours in parallel with the E-cadherin decrease." (PMID 30337687, 2019). "To further validate the correlation of the ZNF185 expression pattern at the protein level in grade 1–grade 3 tumour samples, we performed immunohistochemistry (IHC) staining of ZNF185 in a tissue tumour microarray containing 62 samples of human HNSCC." (PMID 30337687, 2019). "In all cases we saw a significant decrease (p-value: 1.6 × 10−4–2.0 × 10−14) of ZNF185 expression in tumour samples with respect to the normal tissues." (PMID 30337687, 2019). "ZNF185 expression is undetectable at the protein level in poorly differentiated tumour cells of HNSCC tissues compared to well-differentiated tumour cells and normal tissues." (PMID 30337687, 2019). "Altogether, these data demonstrate that ZNF185 expression is dramatically downregulated in the high-grade poorly differentiated SCC tumours, confirming that deregulation of cell adhesion programmes plays a crucial role in epithelial tumour formation." (PMID 30337687, 2019). "We confirmed ZNF185 down-regulation in different epithelial tumours and, by analysing the expression of ZNF185 at protein level, we found a significant decrease of ZNF185 in all the tumour samples analysed." (PMID 30446632, 2018). "All the tumour samples showed a significant decrease (P<1x10-5) of ZNF185 H-score respect to the differentiated layers of the normal epidermis." (PMID 30446632, 2018). "Additionally, the expression of tumor-associated genes such as CT45A3, TPBG, HOXA4, ZNF185, and SNX19 was significantly downregulated." (PMID 40136427, 2025). "The ZNF185 gene expression is involved in the regulation of tumor growth and metastasis." (PMID 38435719, 2024). "In addition, the overexpression of ZNF185 has been shown to promote chemoresistance, tumor proliferation, and inhibition of apoptosis by downregulating SMAD4 in PDAC." (PMID 35111149, 2021). "Of the differentially expressed genes, IFI6, SLC39A9 and ZNF185 showed a strong correlation with tumor progression and patient survival in the OncoLnc database while roles for AKAP12 and DUSP5 in carcinogenesis and poor prognosis have previously been established for other cancer types." (PMID 32849815, 2020).